LINC02532 (long independently transcribed non-coding RNA 2532)
Gene: Long non-coding RNA gene on chromosome 6 (106,705,328 to 106,824,178, reverse strand). Ensembl gene ENSG00000235142.
Diseases named in the same sentence as LINC02532 in open-access papers:
LINC02532 is named in the same sentence as 1 disease in open-access papers, as found by Europe PMC text mining. Sharing a sentence is not in itself a finding about the gene and the disease. The quoted sentences say what the papers report.
gastric cancer (1 paper, 2022). A primary or metastatic malignant neoplasm involving the stomach. "Based on a previous report, LINC02532 is overexpressed in gastric cancer." (PMID 36224753, 2022).